TNF (tumor necrosis factor)
Diseases named in the same sentence as TNF in open-access papers (continued):
Sharing a sentence is not in itself a finding about the gene and the disease.
psoriasis (continued). "During psoriasis development, the increased expression of inflammatory cytokines, such as tumor necrosis factor (TNF)-α, interleukin (IL)-6, IL-17A, and IL-22 triggers uncontrolled inflammatory states and activates keratinocyte hyperproliferation." (PMID 32515468, 2020). "In vitro, the expression of EZH2 and H3K27me3 was stimulated in human keratinocytes treated with mixture of psoriasis-related cytokines pool (TNF-α, IFN-γ, IL-17A, and IL-22)." (PMID 33011750, 2020). "Anti–TNF-a agents have been widely used in Crohn’s disease and other autoimmune-mediated inflammatory diseases, such as rheumatoid and psoriatic arthritis, psoriasis, and ankylosing spondylitis." (PMID 32486412, 2020). "It has been reported that TNFα signaling is involved in IL-24-induced psoriasis like inflammation in mice." (PMID 32153574, 2020). "Real-life studies highlight the clinical benefits of these drugs in different populations and provide evidence that even a change from IL−17 inhibitors to TNF-α or IL−12/23 inhibitors can be a safe and effective therapeutic strategy for long lasting psoriasis." (PMID 32957680, 2020). "TNF-α activates Th17 cells to lead IL-17 production, and the IL-17 inflammatory pathway has been suggested to be important in psoriasis." (PMID 32823524, 2020). "Meanwhile, TNF-α/iNOS-producing dendritic cells (TIP-DCs) play a pivotal role in maintaining psoriasis." (PMID 32121574, 2020). "Accordingly, expression of dominant active S100A8-dimers in a model of TNFα-driven psoriasis-like dermatitis accelerated skin inflammation leading to an aggravated phenotype in mice." (PMID 33643287, 2020). "Psoriasis is considered as a multisystemic disease involving proinflammatory cytokines such as tumor necrosis factor (TNF), interleukin (IL)-1, and IL-173,4." (PMID 32246124, 2020). "To examine the regulation of ET-1 expression in the epidermis in psoriasis, we investigated the expression of ET-1 in human keratinocytes after stimulation with psoriasis-related cytokines such as IL-17A and TNF-α." (PMID 32528072, 2020). "Through the study of the Chinese herb bath in the treatment of psoriasis vulgaris and the relationship between VEGF, TNF- α, IL-23, IL-17 and psoriasis, to lay a theoretical foundation for clinical judgment of psoriasis vulgaris." (PMID 32384509, 2020). "In conclusion, our study shows that paradoxical psoriasis induced by anti‐TNF in patients affected by HS has immunological features common to early phase psoriasis, mainly characterized by cellular and molecular players of innate immunity." (PMID 31577850, 2020). "Accordingly, the interleukin 17 (IL-17) and tumor necrosis α (TNF-α) inflammatory cytokines produced in the skin lesion have been shown to be pathogenically important in the etiology of psoriasis." (PMID 32392785, 2020). "Pro-inflammatory cytokines and adipokines, including TNF-α, play a pivotal role in pathogenesis of both psoriasis and NAFLD as well as in progression of NAFLD to NASH." (PMID 32161545, 2020). "For the treatment of psoriasis, TNF-α antagonists block the effects of TNF-α, a pathogenic cytokine." (PMID 32280718, 2020). "Topical SNAs directed against TNFα and interleukin-17A receptor reversed psoriasis-like disease in mouse models and have been tested in Phase 1 human trials." (PMID 33147737, 2020). "It was found that IL-12/23 inhibitors were associated with lower risks of serious infection in biologic-naïve patients with psoriasis and PsA than TNF inhibitors and IL-17 inhibitors." (PMID 32987907, 2020). "Meanwhile, the expression of inflammatory factors (IL-1β, IL-6, TNF-α, IL-17, and IL-22) in serum and kidney tissue of psoriasis-like mice was significantly increased." (PMID 32090080, 2020). "The first biologics used in the systemic treatment of psoriasis were the tumor necrosis factor (TNF) inhibitors (infliximab, etanercept, adalimumab, golimumab, certolizumab pegol)." (PMID 33270647, 2020).
psoriasis (continued). "At present, the main inhibitors for the treatment of psoriasis are IL-23 inhibitors, IL-17 inhibitors, and TNF-α inhibitors." (PMID 32724829, 2020). "Patients with active psoriasis had significantly higher salivary IL1β, TNF-α, TGF-β, and MCP-1 levels than healthy controls." (PMID 32046271, 2020). "We have also shown that ozone therapy can significantly inhibit inflammatory-related pathways, such as NF-κB, TLR, TNF, and IL-17, in a psoriasis animal model." (PMID 32398953, 2020). "Etanercept is a tumor necrosis factor-alpha blocker that has shown significant therapeutic potency in psoriasis." (PMID 32953323, 2020). "TNF-α concentration in the NWS of psoriasis patients with hyposalivation was significantly higher than in the control group (↑61.38%, p ≤ 0.0001) and in the group of psoriasis patients with normal salivation (↑30.47%, p = 0.009)." (PMID 32164227, 2020). "To test this possibility, we performed co-culture of macrophages with NETs, and measured mRNA expression levels of TNF-α, IL-1β, and IL-36γ, which are involved in the pathological condition of psoriasis." (PMID 33214582, 2020). "The UK study in 2015 (British Association of Dermatologists Biologic and Immunomodulators Register (BADBIR)) and US study in 2016 (PSOLAR) compared the drug survival of TNF-α and IL-12/23 inhibitors in patients with psoriasis." (PMID 32512854, 2020). "In recent years, the dysregulation of these genes, including TNF-α and IL-23, has been shown to participate in the development of psoriasis." (PMID 32121131, 2020). "We chose stimuli known to be relevant in the pathogenesis of psoriasis like IL-17A, IL-17F, TNFα, IL-1α, flagellin as well as murine S100A8 as endogenous Toll-like receptor (TLR)-trigger." (PMID 33643287, 2020). "Since TNF-α is a central point in psoriasis pathogenesis, anti TNF-α therapies have proven a successful treatment." (PMID 32708987, 2020). "Based on the role of immunological factors in the development of psoriasis, therapeutic strategies against TNF-α, IL-23, and IL-17 have been applied in this disorder." (PMID 32695942, 2020). "Systemic inhibition of TNF, IL‐17 and IL‐23 cytokines has revolutionized psoriasis care during the recent decades." (PMID 32757303, 2020). "In vitro CD91+ dendritic cells activated by Hsp70 expressed tumor necrosis factor (TNF)-α—an important proinflammatory cytokine in the immunopathogenesis of psoriasis." (PMID 32239296, 2020). "The expression of these molecules is upregulated in the lesional skin of psoriasis and is downregulated to normal levels by biologics targeting TNF-α or IL-17A." (PMID 32070069, 2020). "In the present study, the imiquimod (IMQ)-induced psoriasis-like mouse model and TNF-α-induced keratinocytes were employed to determine the effects of cimifugin in vivo and in vitro." (PMID 32515468, 2020). "To further clarify the underlying mechanisms involved in MAPK signaling, we assessed MAPK activation in psoriasis and its relationship with the effects of anti-TNF-α therapy." (PMID 32280718, 2020). "Psoriasis is a chronic inflammatory skin disease characterized by accelerated tumor necrosis factor-α/interleukin-23/interleukin-17 axis, hyperproliferation and abnormal differentiation of epidermal keratinocytes." (PMID 32751360, 2020). "Moderate to severe psoriasis management includes using the anti-tumor necrosis factor (TNF) α monoclonal antibodies adalimumab, etanercept and infliximab." (PMID 32403379, 2020). "Crosstalk between the innate and adaptive immune system mediated by various cytokines such as interferon (IFN)-α, tumor necrosis factor (TNF)-α and IL-23, is thought to play an essential part in the onset or exacerbation of psoriasis." (PMID 32456211, 2020). "RA responds to TNF and IL-17A inhibitors; Crohn’s disease, ulcerative colitis, psoriasis, and ankylosing spondylitis respond to TNF and IL-23 inhibitors; atopic dermatitis responds to IL-4 and IL-13 inhibitors." (PMID 32987852, 2020).
psoriasis (continued). "Many cytokines including interferon-gamma (INF-γ), IL-6, and TNF-α have been identified in the pathogenesis of OP, and these are the same as those involved in the inflammation of psoriasis." (PMID 32635380, 2020). "Anti-TNF-α treatment with Infliximab of psoriasis patients significantly reduce the levels of VEGF-A." (PMID 32352958, 2020). "A large retrospective cohort study has demonstrated a significantly reduced incidence of myocardial infarction in psoriasis patients receiving TNF-α inhibitors." (PMID 33053859, 2020). "Paradoxical reactions have been noted for the first time in rheumatoid arthritis patients treated with anti-tumor necrosis factor (TNF) antibodies who developed psoriasis-like skin eruptions." (PMID 32276410, 2020). "Reductions in comorbid cardiovascular events and systemic inflammation have been reported in patients with psoriasis treated with anti-TNF/IL23/IL17 biologics." (PMID 32070069, 2020). "In this study, we found that paradoxical psoriasis evoked by anti‐TNF‐α therapy in patients affected by HS strongly resembles early psoriasis." (PMID 31577850, 2020). "Here, we used ITS1 sequencing to compare the taxonomic diversity of the mycobiome in post-auricular skin samples from psoriasis patients treated with TNF inhibitors (TNFi) and IL-17i with that in samples from those not treated with systemic therapies." (PMID 32486022, 2020). "In psoriasis, proinflammatory cytokines such as tumor necrosis factor-alpha (TNF-α) and interleukin (IL)-6 induce endothelial dysfunction, thereby increasing the risk of cardiovascular disease and increasing the incidence of cerebral ischemic disease." (PMID 33322823, 2020). "Tumor necrosis factor alpha (TNF-α) was reduced in psoriasis (p = 0.04) and CFS (p = 0.02), while interleukin (IL)-6, for example, was reduced in CFS (p = 0.05) and UC (p = 0.06)." (PMID 32698454, 2020). "Among the several pro-inflammatory cytokines involved in psoriasis, TNF-α, IL-6, and IL-12 are usually increased in psoriatic patients, creating a negative loop that exacerbates the inflammatory condition." (PMID 32059361, 2020). "The participation of macrophages in the pathogenesis of psoriasis has been previously suggested with a key role for TNF and IL-1β." (PMID 32269570, 2020). "Inflammation in psoriasis patients is effectively treated with biological agents – tumor necrosis factor-α (TNF-α) inhibitors such as infliximab, adalimumab, and etanercept; ustekinumab (interleukin [IL]-12/23 inhibitor), and secukinumab (IL-17 inhibitor)." (PMID 32881431, 2020). "The accelerated TNF-α/IL-23/IL-17 axis is the major pathomechanism of psoriasis; dendritic cells (DCs) activated by various stimuli in the lesional skin secrete TNF-α which acts on themselves in an autocrine manner and induces IL-23 secretion." (PMID 32751360, 2020). "It was proved that IL-23/T help (Th)-17 immune axis, IL-1 and TNF-α played a central role in the pathogenesis of psoriasis." (PMID 32090080, 2020). "Chloroquine or TCDD treatment of psoriasis skin biopsies enhanced the production of the proinflammatory cytokines, IL-1β, IL-6, and TNF-α compared to chloroquine- or TCDD- treated controls." (PMID 32235789, 2020). "There are case reports of patients with psoriasis and other immune-mediated inflammatory diseases who developed uveitis after exposure to TNF-alpha inhibitor." (PMID 32724820, 2020). "In psoriasis skin biopsies, the synthesis of proinflammatory cytokines, including IL-1β, IL-6, and TNF-α, was significantly enhanced by TCDD and chloroquine, compared to controls." (PMID 32235789, 2020). "Although we have used a mouse model to study psoriasis-like disease, it is clinically reported that patients with active psoriasis have elevated levels of TNF-α in blood serum and skin lesions." (PMID 31991752, 2020). "The existing evidences show that TNF-α blockers are effective in the treatment of chronic inflammatory disorders, such as psoriasis." (PMID 33364982, 2020).
psoriasis (continued). "Genistein had positive effect on the treatment of psoriasis by inhibiting TNF-α-induced I-kBα phosphorylation and p65 nuclear translocation." (PMID 32083119, 2019). "Anti-TNF is used for treating psoriasis in case of therapeutic failure or contraindication of methotrexate." (PMID 31101850, 2019). "A fall in the hormone levels, especially estrogen, during menopause is believed to result in higher production of IL-12 and TNF-α and thereby to a higher antigen presentation rate of dendritic cells leading to a worsening of psoriasis." (PMID 31744488, 2019). "Recently, a few studies have been conducted to elucidate the mechanism of action of these anti-TNF agents in the resolution of psoriasis, focusing on different gene expression in psoriatic lesion and peripheral blood." (PMID 30953507, 2019). "In the past decade, biologics targeting tumor necrosis factor-α, interleukin (IL)-23, and IL-17 have been developed and approved for the treatment of psoriasis." (PMID 31491865, 2019). "This study successfully optimized the components of the desired PDT system, a combination of Cur-CS/Alg NPs and blue LED light, for the treatment of TNF-α-induced psoriasis-like proliferation of keratinocytes." (PMID 30970577, 2019). "The in vitro findings of slanMo producing TNF-α and IL-23 are mirrored by studies on psoriasis skin lesions where 85% of dermal slanMo were found to express IL-23p19 and 50% of the cells expressed TNF-α." (PMID 31191513, 2019). "They therefore proposed a model mechanism of TNFα inhibition in psoriasis where inflammatory DCs are quickly inhibited, in turn repressing Th17 response and keratinocyte hyperproliferation." (PMID 31673756, 2019). "All patients, on the day preceding the therapeutic pulse (day 0), presented more psoriasis symptoms than on day 7, after receiving TNF inhibitors." (PMID 31101850, 2019). "The production of pro-inflammatory cytokines TNF-α, IL-6, IL-12p40, and IL-23 of the hPBMCs from the psoriasis patients were significantly higher than that of the healthy subjects (P < 0.001)." (PMID 31291937, 2019). "In this study, the effect of ghrelin on NF-κB signaling was examined in OXA-induced contact dermatitis and IMQ-induced psoriasis mouse models, as well as TNF-α-treated RAW264.7 cells." (PMID 30718736, 2019). "It is well known that psoriasis and HS likely share immunopathogenetic pathways, including involvement of IL-17 and TNF." (PMID 33456757, 2019). "Like IL-17 and IFN-γ, TNF-α is a crucial cytokine in the inflammatory process of psoriasis, and it is produced by cells of both the innate and adaptive immune systems." (PMID 31101850, 2019). "Blocking of the TNF-α, the NF-κB pathways have been a focus of the anti-psoriasis treatments as it leads to the reduction in the inflammasome activation and downregulation of the cytokine such as IL-1β." (PMID 31680964, 2019). "After silencing IL37, cells were stimulated with a mixture of five cytokines designated as M5 (IL-1α, IL-17A, IL-22, Oncostatin M, and TNF-α) to mimic the microenvironment of keratinocytes in psoriasis." (PMID 30918469, 2019). "There was a significant reduction in the production of IFN-α and TNF-α, a cytokine critical for the initiation of psoriasis, in cells treated with IMQ and R848." (PMID 31447855, 2019). "Current therapies for psoriasis include the use of targeted biologics such as anti-TNFα, anti-IL-17A and anti-IL-23 antibodies for moderate to severe patients." (PMID 31235749, 2019). "The excellent therapeutic efficacy of anti-TNF-α/IL-23/IL-17A biologics for psoriasis point to the central role of the TNF-α/IL-23/IL-17A axis in its pathogenesis Additionally, genetic and environmental factors are known to be involved in its pathogenesis." (PMID 31683543, 2019). "Inhibition of TNFα and IL-23 signaling nodes are clinically validated approaches for the treatment of psoriasis in patients." (PMID 31776355, 2019).
psoriasis (continued). "Of note, this variant has not been identified in diseases that are ameliorated by inhibition of TNF, such RA, psoriasis, and Crohn's disease." (PMID 30941119, 2019). "In the immunopathogenesis of psoriasis, TNF-α promotes the activation and maturation of DCs, which, in turn, produce more IL-2320." (PMID 31101850, 2019). "Th17 cells, and to a lesser extent Th1 cells, are crucial for orchestrating the chronic, maintenance phase of psoriasis, and, as such, the p40 subunit presents a more specific target for psoriasis compared to TNF-α." (PMID 31590274, 2019). "An excellent therapeutic response to biologics indicates a pivotal pathogenic role of interleukin (IL)-4/IL-13 signaling in AD and the tumor necrosis factor (TNF)-α/IL-23/IL-17A axis in psoriasis." (PMID 31683543, 2019). "In this study, we analyzed 32 patients with psoriasis; ten of them under treatment with TNF inhibitors, receiving one dose each 15 days." (PMID 31101850, 2019). "Biological agents (Etanercept, Infliximab and adalimumab) targeting TNF- α have showed high efficacy in psoriasis therapy, which consists with the pivotal role of TNF- α in the pathogenesis of psoriasis." (PMID 30953507, 2019). "In psoriasis, a combination of the inflammatory cytokines IL-17, TNFα, IL-22, and IFNγ drives keratinocyte hyperproliferation and cytokine and chemokine release." (PMID 31673756, 2019). "In the imiquimod-induced psoriasis mouse model, the intradermal administration of ADMSCs inhibits IL-17A and TNF-a, and suppresses the IMQ-induced inflammation." (PMID 31824416, 2019). "In the case of paradoxical psoriasis, a TNFi-induced cytokine imbalance between TNF-α and type 1-Interferons (IFN-α) has been reported as key-pathogenetic factor." (PMID 30971924, 2019). "Twenty-four hours after the eighth application of IMQ on day 7, the mRNA expression of TNF-α, IL-12/IL-23, IL-17, and IL-22 increased in psoriasis-like dermatitis as compared with that in control mouse skin." (PMID 30838224, 2019). "Studies have shown increased levels of TNF-α in the skin tissues and blood samples of contact dermatitis and psoriasis patients, and treatments that inhibit activation of TNF-α display significant efficacy in both contact dermatitis and psoriasis." (PMID 30718736, 2019). "Psoriasis is mediated by a plethora of cytokines and chemokines where TNF-α and the IL-23/IL-17 axis play an outstanding role." (PMID 31417571, 2019). "TNF-α has been studied as one of the main inducers of skin diseases, including contact dermatitis and psoriasis." (PMID 30718736, 2019). "Overall, these findings demonstrated a domino effect model of anti-TNF- α action in improving psoriasis, which need to further clarify at a systemic level especially using a standardized protocol for method analysis." (PMID 30953507, 2019). "Proteinase 3 cleaves and converts the resting TNFα located in membrane of epithelial cells (mTNFα) to an activated state called soluble TNFα (sTNFα), which participates in the psoriasis complex inflammatory reactions." (PMID 31649677, 2019). "Since CZP is an anti-TNF drug, therapies which have good clinical response in both psoriasis/psoriatic arthritis and HS, it was chosen as the treatment of choice in our case since it also has a safe profile for possible future pregnancy." (PMID 33456757, 2019). "As a pro-inflammatory cytokine, TNF- α possesses multiple activities in the development and maintenance of psoriasis, including recruiting T cells to the skin and increasing the proliferation of keratinocytes." (PMID 30953507, 2019). "Patients (n = 38) taking antagonists of tumor necrosis factor (these drugs are widely used as agents for the treatment of psoriasis), were divided into 2 groups." (PMID 31238561, 2019). "The Interleukin-23 (IL-23)/IL-17/IL-22 cytokine axis, TNF-α, and IL-1β are important inflammatory mediators in the pathogenesis of psoriasis." (PMID 31252620, 2019).